ENSG00000173867 (novel transcript)
Gene: Protein-coding gene on chromosome 15 (88,459,501 to 88,546,585, reverse strand). Ensembl gene ENSG00000173867.
Genetic constraint (gnomAD): Loss-of-function variants: 22 observed, 45.4 expected, observed/expected ratio (o/e) 0.48, 90% interval 0.34 to 0.69. Missense variants: 713 observed, 743.52 expected, observed/expected ratio (o/e) 0.96, 90% interval 0.9 to 1.02. Synonymous variants: 315 observed, 280.92 expected, observed/expected ratio (o/e) 1.12, 90% interval 1.02 to 1.23.